ALB (albumin)
Diseases named in the same sentence as ALB in open-access papers (continued):
Sharing a sentence is not in itself a finding about the gene and the disease.
diabetes (continued). "Additionally, deceased patients with diabetes also had lower levels of HgB, serum albumin and eGFR, but higher levels of fasting glucose and proteinuria." (PMID 36650566, 2023). "A multivariate linear regression model was constructed for the TyG index; the regression analysis results revealed significant (p < 0.05) increases in Upcr (log value), diabetes, WC, BMI, hemoglobin level, TG level, and albumin level with an increasing value in TyG index." (PMID 37255931, 2023). "In univariate analysis, older age, male sex, BMI, diabetes, hypertension, low albumin levels, high globulin levels, and intermediate to high probability of liver fibrosis according to the NFS, FIB-4, and FIB-8 were significantly associated with a higher risk of severe COVID-19." (PMID 37823314, 2023). "In multivariate models that adjusted for age, BMI, diabetes, cardiovascular diseases, prevalent fractures, serum albumin, and CRP, which were variables with P < 0.05 in univariate analyses, serum magnesium levels were independently associated with increased CFS scores (β = − 0.126, P = 0.005)." (PMID 37696942, 2023). "In model 2, was Model 1 plus; diabetes, serum albumin and age." (PMID 37497059, 2023). "The trend of OR value of both glucose and albumin implied the risk role of GAR in adults without diabetes for NAFLD, although the P-value for albumin was not significant due to the limitation of online GWAS profiles." (PMID 38264288, 2023). "The urinary albumin-to-creatinine ratio increased rapidly after diabetes induction." (PMID 37240387, 2023). "Moreover, urinary PDGF-BB was positively correlated with LDL, urinary albumin, and disease duration, but negatively correlated with creatinine clearance in patients suffering from diabetes mellitus." (PMID 38202116, 2023). "Both manifestations of kidney disease in diabetes, reduced eGFR (ml/min per 1.73 m2) and increased urinary albumin/creatinine ratio (UACR, mg/mmol), may increase the risk of specific CVD subtypes in adults with diabetes." (PMID 36347992, 2023). "In the animal model of diabetes, the kidney/body weight, levels of blood glucose and serum bilirubin, and urine albumin-creatinine ratio (UACR) had significantly increased, these factors, especially UACR and bilirubin, showing overall improvements with mPTD-BMP7 treatment (P<0.05)." (PMID 37293506, 2023). "In the univariable logistic regression analysis, 2187 CpGs were associated with the risk of CKD development, and 457 CpGs remained significant in the multivariable logistic regression analysis adjusted with age, sex, baseline eGFR, hypertension, diabetes mellitus, and serum albumin level." (PMID 37510393, 2023). "LASSO regression was applied for the training set to obtain nine variables including age, monocytes, neutrophils, serum albumin, serum potassium, cardiovascular disease, diabetes, serum creatinine and glycated hemoglobin (HbA1C), and constructed a nomogram prediction model." (PMID 38074152, 2023). "Indeed, their use with blood samples can provide a measurement of the concentration of glycated hemoglobin and glycated albumin, two well-known diabetes markers." (PMID 37903872, 2023). "Meanwhile, some variables were also found significantly associated with technique failure, including age, history of coronary heart disease, history of diabetes, history of using statins, albumin, phosphorus, N-terminal pro-brain natriuretic peptide (NT-proBNP) and glucose (p < 0.05)." (PMID 37009921, 2023). "For these calculations, pre-donation variables such as age, gender, race, donor–recipient relation, diabetes in the donor, diabetes in the recipient, eGFR, blood pressure, hypertension medication, BMI, smoking, urine albumin/creatinine ratio, and glucose are used." (PMID 35329811, 2022).
diabetes (continued). "The model was built using the following variables: age, male sex, black race, current smoker, systolic blood pressure, use of antihypertensive medication, diabetes mellitus, serum potassium, serum albumin, high-density lipoprotein, estimated glomerular filtration rate and the corrected QT interval." (PMID 35327441, 2022). "Our study further confirms that low preoperative albumin levels, diabetes, history of rheumatic disease, and intraoperative dural tear are risk factors for surgical site infection after posterior lumbar interbody fusion, which is consistent with previous findings." (PMID 36050996, 2022). "In the setting of cardiac disease including myocardial infarction, heart failure, and cardiac surgeries, increased risk of AKD was associated with age, female sex, AKI stage, diabetes, baseline CKD, hemoglobin, albumin, BNP, inotrope use, and outpatient loop diuretic use." (PMID 36340722, 2022). "In this way, the positive association between OPG and diabetes, age, systolic blood pressure, calcium, vascular calcifications, as well as the negative correlation with serum albumin, found in the present study, can be explained." (PMID 35454141, 2022). "White Blood Cell Count (Wbcc), Blood Glucose Random (bgr), Blood Urea (Bu), Serum Creatinine (Sc), Packed Cell Volume (Pcv), Albumin (Al), Hemoglobin (Hemo), Age, Sugar (Su), Hypertension (Htn), Diabetes Mellitus (Dm), and Blood Pressure (Bp) are examples of these traits." (PMID 35206985, 2022). "The univariate analysis results showed significant differences concerning the incidence of preoperative tension blisters, smoking history, history of diabetes, preoperative haemoglobin, preoperative albumin, time from injury to surgery, and operation time between the two groups (p < 0.05)." (PMID 36514037, 2022). "Also, the key features selected by the MQGWO-FKNN model were analyzed with physiological significance, including age, dialysis vintage, diabetes, and baseline albumin." (PMID 36387587, 2022). "Our retrospective study confirmed that the BIA-derived PA, measured at 50 kHz, was associated with biochemical and anthropometric nutritional parameters, such as serum albumin, creatinine, and cholesterol levels, BMI, and clinical parameters such as a history of diabetes mellitus and CAD." (PMID 35758371, 2022). "The NFS is the most common simple scoring system, and it consists of seven regular clinical and laboratory indices, including age, diabetes status, platelet counts, albumin, BMI, ALT, and AST, to predict advanced liver fibrosis and reflect the progression of liver injury in patients with NAFLD." (PMID 34996457, 2022). "We have found that the incidence of AKI in PNS patients is 28.05%, and diabetes, pulmonary infection, albumin ≤ 24 g/L, serum creatinine ≥ 90 μmol/L, blood urea nitrogen ≥ 6.5 mmol/L, uric acid ≥ 390 μmol/L, renal tubular casts are the independently influencing factors of AKI in PNS patients." (PMID 35247980, 2022). "Univariate Cox regression analysis revealed that age, male sex, diabetes mellitus, hypertension, cirrhosis, higher liver stiffness values, lower platelet counts, higher AST, higher ALT levels, and lower serum albumin levels were significantly associated with the development of HCC (all p < 0.05)." (PMID 35158982, 2022). "Long dialysis vintage (p = 0.006, OR = 2.25), the presence of diabetes (p = 0.037, OR = 1.81), low serum albumin levels (p = 0.047, OR = 0.54), high serum calcium levels (p = 0.046, OR = 2.04) and pulse pressure (p < 0.001, OR = 3.22) were independent risk factors for CVC in ESKD patients." (PMID 35166181, 2022). "In the case of diabetes mellitus, albumin synthesis relies on adequate insulin reserves." (PMID 36344933, 2022). "Besides, the high RDW population also had significantly lower albumin level and increased rate of comorbidities with diabetes, hypertension, and chronic kidney disease." (PMID 35205691, 2022).
diabetes (continued). "Glycated albumin seems to be a better biomarker than HbA1C in cases of diabetes mellitus." (PMID 35942243, 2022). "We recorded the patients’ age, sex, primary disease, MRONJ stage, type and administration period of the AR agent, presence of diabetes, corticosteroid use, drug holiday period, white blood cell count, serum albumin, serum creatinine, outcomes, and computed tomography findings." (PMID 35457491, 2022). "Our current study, similar to this study, adjusted for several potential confounders such as CHD, hypertension, diabetes, SCr, SUA, and blood lipid profiles; moreover, the results of our study were supported by this study reporting that serum ALB was inversely associated with AF." (PMID 36031606, 2022). "Diabetes mellitus (p = 0.0076), serum albumin level (p = 0.030), Eastern Cooperative Oncology Group Performance Status (ECOG PS) (p = 0.0007), serum CA19–9 level (p = 0.0028), and peripheral CD4+ T cell ratio (p = 0.011) were significantly associated with prognosis in multivariate analyses." (PMID 36333670, 2022). "We also evaluated the relationship between FA abundance and other clinical factors that may contribute to sarcopenia, including age, body mass index (BMI), diabetes status, and levels of hemoglobin and albumin." (PMID 35269531, 2022). "Therefore, screening of neutrophil counts, CRP, ALP, serum lactate and albumin levels is advised in diabetic cancer patients infected with SARS-CoV-2." (PMID 36059615, 2022). "In univariate analysis, prevalent CAC at baseline was associated with age, male sex, diabetes mellitus, CVD, lower diastolic blood‐pressure, estimated glomerular filtration rate (eGFR), PEW, body mass index (BMI), FRS, lower hand grip strength, lower albumin, hsCRP, IL‐6, and AVC." (PMID 35112417, 2022). "TIM was negatively correlated with the duration of renal replacement therapy, dialysis modality, dialysis treatment time per week, and albumin and was positively correlated with age, residual urinary output, a diagnosis of diabetes or previous myocardial infarction, and statin treatment." (PMID 35453489, 2022). "Besides, some characteristics were found related to higher urinary albumin level in both samples, including lower education, obese, insufficient physical activity, hypertension, and diabetes." (PMID 35020733, 2022). "To investigate the joint effect of UFR and postdialysis weight on survival, we fit Cox proportional hazards models using bivariate tensor product spline functions, adjusting for sex, race, age, diabetes, and predialysis serum albumin, phosphorus, and systolic blood pressure (BP)." (PMID 35812299, 2022). "Univariate analysis showed that the factors with statistical significance (P < 0.05) were age, number of fusion levels, intraoperative dural tear, diabetes, history of rheumatic disease, preoperative red blood cell count, preoperative albumin level, and ASA grade." (PMID 36050996, 2022). "Six variables, including hemoglobin, albumin, length of operation time, American Society of Anesthesiologists grades, presence of traumatic subarachnoid hemorrhage, and a history of diabetes, were selected from 37 variable candidates as the top-weighted prediction features." (PMID 35887741, 2022). "Catabolism of albumin may be increased by glycosylation, which is known to occur in 2‐ to 3‐fold increases in patients with diabetes." (PMID 36116062, 2022). "The albumin levels and the prevalence of diabetes, but not the copper levels, were also associated with the SPP." (PMID 35128488, 2022). "In diabetics with progressive renal dysfunction, urinary excretion of this element may be due to dissociations of both albumin–copper and ceruloplasmin–copper complexes filtering through the damaged glomerulus." (PMID 36676942, 2022). "The induction of diabetes resulted in deteriorated hepatic function, as revealed by significant increases in the serum liver enzyme activities and bilirubin accompanied by a significant decrease in serum albumin." (PMID 35629430, 2022).
diabetes (continued). "Pearson correlation analysis showed that diabetes(r = 0.688), pulmonary infection (r = 0.614), albumin (r = 0.779), serum creatinine (r = 0.617), uric acid (r = 0.522), blood urea nitrogen (r = 0.616), renal tubular casts (r = 0.707) were correlated with AKI in PNS patients (all P < 0.05)." (PMID 35247980, 2022). "The estimated glomerular filtration rate (eGFR) and the degree of albuminuria measured by the albumin-to-creatinine ratio (ACR) are routinely measured in people with diabetes and are recognised as prognostic indices for kidney outcomes, cardiovascular outcomes, and death." (PMID 35996147, 2022). "CC has also been reported to be an independent factor of frailty after adjusting for confounders such as age, sex, anthropometric indicators (BMI, WC, and HGS), and biological markers (hemoglobin, albumin, creatinine, and HbA1c) among Chinese patients aged ≥80 years with diabetes." (PMID 36568803, 2022). "The main goal of this study was to evaluate the effect of a mixture of fatty acids (FA) on the affinity of losartan (LOS, an angiotensin II receptor (AT1) blocker used in hypertension, a first-line treatment with coexisting diabetes) for glycated albumin—simulating the state of diabetes in the body." (PMID 35056715, 2022). "In another study, HbA1c, plasma Cr, albumin-creatinine ratio, HDL-C, age, sex, smoking, and diabetes duration were all associated with skin AGEs, again showing that this pathway may be especially relevant in certain risk groups." (PMID 35879776, 2022). "Decreased levels of albumin might act as a factor that contributes to the development of numerous oxidative stress-related disorders, such as diabetes and cancer." (PMID 36139738, 2022). "Specifically, Black men presented with lower hemoglobin (p=0.04), higher creatinine (p=0.05), lower albumin (p=0.001) levels, higher prevalence of diabetes (p=0.05), and more weight loss (p=0.05) than non-Black men." (PMID 35693376, 2022). "The indicators to be collected for this study include gender, age, body mass index, preoperative liver function (total bilirubin, alanine aminotransferase, and albumin), preoperative comorbidities (diabetes, chronic pancreatitis), and pancreatic condition (texture, pancreatic duct diameter)." (PMID 35669237, 2022). "For example, we note that obese mice could be studied in order to test if reduced plasma FFA through targeting albumin could lead to a reduced propensity toward diabetes and fatty liver disease." (PMID 35238481, 2022). "In addition, after adjusting for age, background CVD, diabetes, BMI, serum albumin, serum Angpt-2, RRF, and PD duration, the predictive effect of Pcl on all-cause mortality was lost." (PMID 35721057, 2022). "A previous meta-analysis showed that the addition of urinary albumin-to-creatinine ratio (UACR) and GFR significantly improved the prediction of mortality and cardiovascular outcomes beyond traditional risk factors in patients with diabetes mellitus." (PMID 35721762, 2022). "Age, the duration of diabetes, the utilization of acarbose, triglyceride (TG) level, albumin level, fibrinogen level, hemoglobin level, neutrophil percentage, platelet count, and neutrophil/lymphocyte ratio (NLR) level were all significantly different between the four subgroups (p < .05)." (PMID 36712669, 2022). "The relationship remained significant after adjusting for albumin, gender, and diabetes." (PMID 35055386, 2022). "Conversely, a higher percentage of IFS patients had comorbidities, such as diabetes mellitus and hematologic malignancy, which may have led to differences in blood glucose, HbA1c, Hb levels, albumin levels, and leukopenia among these two groups." (PMID 36547572, 2022). "Also, endurance exercise with moderate intensity for four weeks before induction of diabetes decreases urinary albumin levels after the injury." (PMID 35236328, 2022).
diabetes (continued). "After adjusting for age, sex, the presence of diabetes mellitus, plasma hemoglobin, serum albumin, serum potassium, and LVSD, serum cortisol remained an independent risk factor for patient mortality (hazard ratio 1.234, 95% confidence interval 1.022-1.49, P=0.029)." (PMID 35260104, 2022). "Patients with a longer diabetes duration (≥6 years (72 months)), lower eGFR (<60 mL/min/1.73 m2), lower albumin (<30 g/L), lower hemoglobin (<120 g/L), and a higher grade of glomerular damage (class III + IV vs. class I + II) achieved a worse prognosis significantly (p < 0.05)." (PMID 36614886, 2022). "Diabetes and periodontitis were linkedto lower salivary uric acid and albumin levels." (PMID 37693919, 2022). "In addition, an adjustment of the ECW/TBW ratio is known to be necessary for patients with diabetes, hypoalbuminemia (albumin < 3.5 g/dL), and heart disease." (PMID 35300597, 2022). "The factors contributing to dysglycemia included disease severity, insulin treatment, glucocorticoid use, serum albumin level, total parenteral nutrition, duration of diabetes, elevated procalcitonin level, and need for mechanical ventilation and renal replacement therapy." (PMID 34761326, 2022). "However, the fast peritoneal transporter group had a higher proportion of individuals with diabetes mellitus, older patients, and patients with lower serum albumin levels (p < 0.001)." (PMID 36426736, 2022). "We did not detect effect modification on the basis of sex, race, ethnicity, vintage, vascular access type, insurance status, BMI, diabetes status, cardiovascular disease status, serum phosphorus, serum albumin, serum creatinine, nPCR, spKt/V, of dietary protein intake levels." (PMID 35893923, 2022). "This may be particularly important in patients with diabetes or CKD, where increased glycation and carbamylation of albumin, associated with high glucose or urea levels, could lead to overloading of lysosomes and a reduced serum half-life of albumin." (PMID 35378997, 2022). "Patients in the NDD-CKD group had a higher prevalence of hypertension, diabetes, and dyslipidemia; lower hemoglobin, protein, albumin, and phosphate levels and red blood cell counts; and higher blood urea nitrogen and creatinine levels than those in the NC group." (PMID 36588888, 2022). "We also found negative associations with serum insulin in diabetes and albumin (weak correlation each), but HDL-c was not correlated with biochemical parameters." (PMID 35462799, 2022). "We used age, gender, race, education, hypertension, diabetes, pain elsewhere, moderate activity, vigorous activity, smoking, drinking, BMI, waist circumference, albumin, phosphorus, total calcium, triglycerides, cholesterol, vitamin D, and eGFR as input variables." (PMID 36199766, 2022). "Finally, we determined ALB in the offspring mice, and the results showed that maternal diabetes (STZ‐HSCT/STZ/EMP) treatment significantly decreased USVs." (PMID 35220596, 2022). "Services like distribution of conventional contraceptives, testing for malaria, urine albumin/sugar, haemoglobin estimation, screening for diabetes and hypertension, sputum collection, and qualitative iodine test kits are not available in any of the UHND sessions." (PMID 34643347, 2021). "When the baseline data of patients were compared based on the different types of peritoneal transport status, a significant difference in the mean age, the proportion of patients diagnosed with diabetes mellitus, and levels of serum albumin were observed between the groups." (PMID 34233593, 2021). "Based on the results of statistical analyses, these two groups were homogenous for age, gender, body mass index, blood pressure, proportion of diabetes mellitus and cardiovascular disease, and the concentrations of serum albumin, triglycerides, and cholesterol (all p > 0 0.05)." (PMID 34579742, 2021).